BRCA1 (BRCA1 DNA repair associated)
Diseases named in the same sentence as BRCA1 in open-access papers (continued):
Sharing a sentence is not in itself a finding about the gene and the disease.
breast cancer (continued). "The aim of our study was to investigate the frequency of the deleterious BRCA1: p.Ile1845fs variant in breast carcinomas, as well as the correlation between p.Ile1845fs variant with clinicopathological parameters and clinical outcomes." (PMID 31908633, 2020). "A study among Japanese women found a similar prevalence of high penetrance BRCA1/2 variants in women with invasive and breast carcinoma in situ." (PMID 33148280, 2020). "Women who have inherited pathogenic variants (mutations) in the BRCA1 and BRCA2 genes (BRCA1/2) face a very high lifetime risk of developing breast cancer (BC) and/or ovarian cancer (OC)." (PMID 33266155, 2020). "Inherited pathogenic variants (PVs) in BRCA1 or BRCA2 genes cause a significantly increased risk for breast cancer (BC), ovarian cancer (OC) and other tumors including pancreas and prostate cancer." (PMID 32380732, 2020). "Using the vagina as a natural orifice, we performed a transvaginal laparoscopic salpingo-oophorectomy to remove bilateral adnexa in patients with a strong family history of ovarian and/or breast cancer and those positive for BRCA1/2 mutation." (PMID 31915530, 2019). "Breast cancer risk for late onset cases (above 70 years old) who carry pathogenic mutation in BRCA1 and BRCA2 is 57 and 50%, respectively." (PMID 31477031, 2019). "Hereditary breast and ovarian cancers are primarily related to highly penetrant germline mutations in either one of the two breast cancer susceptibility genes, BRCA1 and BRCA2." (PMID 30915162, 2019). "Consistent with our results, SIRT5 was shown to be overexpressed in human NSCLC, triple-negative breast cancer, breast cancer with BRCA1 mutation subtypes, CRC, and HCC." (PMID 31456942, 2019). "Germ-line mutations in the breast cancer genes BRCA1 and BRCA2 result in predisposition to breast and ovarian cancers (BRCA1) as well as other cancers (BRCA2)." (PMID 31890056, 2019). "In current practice for breast cancer prediction, there is a focus on presenting risk of breast cancer over time and/or likelihood of being a carrier of a BRCA1 or BRCA2 pathogenic variant (PV)." (PMID 30832243, 2019). "Most breast cancer cases are sporadic; however, approximately 5% of breast cancers are attributable to germline BRCA1 or BRCA2 mutations." (PMID 31454914, 2019). "Bhatta (2016) reported the mean age of onset of breast cancer was 42.59 years and found 8% of BRCA1 mutation in his study population in Nepal." (PMID 31759379, 2019). "Among the 35 (24%) BRCA-mutated breast cancer patients, 22 and 13 harbored deleterious BRCA1 or BRCA2 mutations, respectively." (PMID 31355134, 2019). "This is the first study to demonstrate the association of the BRCA1 expression level and the T cell activation score, and their interaction in patient survival in breast cancer." (PMID 31023256, 2019). "Genetic screens are increasingly being offered for the identification of pathogenic variants, which increase the risk of developing breast cancer, in BRCA1, BRCA2 and other breast cancer genes." (PMID 30832243, 2019). "BRCA1/2 mutations and BrCAness are a hallmark of familial basal-like breast cancer, but sporadic TNBCs are poorly defined in the clinic." (PMID 31836816, 2019). "The identification of deleterious mutations in the breast cancer susceptibility genes BRCA1 and BRCA2 has important implications for mutation carriers in general, because they are the principal cause of Hereditary Breast and/or Ovarian Cancer Syndrome." (PMID 30652428, 2019). "More specifically, mutations in the DNA-damage repair (DDR) gene BRCA1 alone can increase the probability of developing breast cancer before the age of 80 from 12 to 75%." (PMID 31775907, 2019). "Before a significant number of breast cancer cases were cured through modern health care, young onset breast cancer was a common cause of death in the path_BRCA1 carriers." (PMID 30678073, 2019).
breast cancer (continued). "BRCA1-mutated breast cancer show low prevalence of calcifications on mammogram, more common with BRCA2 mutation." (PMID 31781977, 2019). "Incidentally, young age of diagnosis, high-grade tumours, triple-negative breast cancers, and basal-like subtype are known to be associated with BRCA1-deficient breast cancers." (PMID 31022191, 2019). "The results of the comparison of the breast cancer subtypes between the three groups were as follows: triple-negative breast cancer accounted for 89% of the BRCA1 L63X mutation group, 64.4% of other BRCA1 group, and 21.2% of BRCA2 group (p < 0.001)." (PMID 31143373, 2019). "Here, we report the functional characterization of the unclassified BRCA2 c.8299C > T variant, identified in a young breast cancer patient during BRCA1/2 NGS screening." (PMID 31569370, 2019). "She had multiple first-degree relatives with breast cancer; however, she was found to have a concomitant BRCA1 germline mutation, c.3817C>T." (PMID 31125277, 2019). "Germline mutations in BRCA1 and BRCA2 (BRCA1/2) genes are present in about 50% of cases of hereditary breast cancer." (PMID 31658756, 2019). "The exact cancer risks of many newly discovered genes are not always known, and some genes appear to convey a moderately increased risk of breast cancer compared with the high risk associated with BRCA1/2." (PMID 31890060, 2019). "Several studies have reported higher rates of breast cancer 1 and 2 (BRCA1 and 2) gene mutations in Ashkenazi Jewish women." (PMID 31408930, 2019). "In cancer predisposition genes, there are 25 globally known SNPs identified to increase risk of breast cancer and of the 25, 14 SNPs are located in BRCA1 and BRCA2 genes." (PMID 31131559, 2019). "That’s why this study is carried out to identify BRCA1 gene mutations in Bangladeshi female patients with breast cancer." (PMID 31759379, 2019). "Cumulative lifetime risks (until age 80 years) of breast cancer associated with BRCA1/BRCA2 mutations are estimated to be as high as 72% (65–79%) and 69% (61–77%), respectively, while ovarian cancer risks are 44% (36–53%) and 17% (11–25%)." (PMID 30689103, 2019). "Here, the authors sequenced DNA from more than 5,000 Swedish breast cancer patients looking for pathogenic BRCA1/2 variants, and they found 92 carriers." (PMID 30175445, 2019). "Women, who carry a germline BRCA1 gene mutation, have a markedly increased risk of developing breast cancer during their lifetime." (PMID 31771627, 2019). "We next analyzed the mutational landscape of the 80 BRCA1-deficient breast cancer cases, focusing on deleterious mutations, amplifications and homozygous deletions." (PMID 30674894, 2019). "BRCA1 was the first identified breast cancer susceptibility gene and is currently the newest member of the FA family." (PMID 31320901, 2019). "In the group of carriers of the BRCA1 mutation, the lifetime risks of developing ovarian and fallopian tube cancers oscillate around 15% and 54%, respectively, and the risk of breast cancer ranges from 60% to 80%." (PMID 31818005, 2019). "Genetic testing that assesses the risk of breast cancer (BRCA1 and BRCA2) is currently only offered in university hospitals or highly specialized centers to help identify women with a family history of cancer who would benefit from early screening." (PMID 31155002, 2019).
breast cancer (continued). "Olaparib, a PARP inhibitor, showed considerable benefit in patients with metastatic BRCA1-mutated breast cancers." (PMID 31413819, 2019). "Mutations of BRCA1 RING domain lead to breast cancer by disrupting the E3 ubiquitin ligase activity of BRCA1-BARD1." (PMID 30975222, 2019). "As a result, patients with mutated BRCA1/BRCA2 are suitable candidates for additional treatment with PARP inhibitors, such as the recently approved drug olaparib which was approved in 2019 in Europe for germline BRCA1/2-mutated HER2− breast cancer." (PMID 31921847, 2019). "A total of 62 breast cancer patients were treated, and 60% of these breast cancer patients had a BRCA1 mutation." (PMID 30934991, 2019). "It is shown to reduce breast cancer risk by at least 95% in women with BRCA1 or BRCA2 mutation and by 90% for those with a strong family history." (PMID 31267556, 2019). "To analyse the prevalence of breast cancer with BRCA1/2 genetic variants, we screened BRCA1/2 variants in the 25 recruited patients with personal and family history of breast cancer." (PMID 31131559, 2019). "Increased PD-L1 expression is identified in breast tumors deficient in DNA repair, and infiltrating immune-cell PD-1 and PD-L1 expression is higher in breast cancers with BRCA1 or BRCA2 mutations." (PMID 31320901, 2019). "From these data, short‐term hematologic toxicities during breast cancer chemotherapy appear similar which should be reassuring for clinicians administering, and patients with a BRCA1 or BRCA2 mutation receiving, chemotherapy." (PMID 31407530, 2019). "A BRCA1 mutation can be detected in 52% of breast cancer patients and up to 80% have a mutation in either BRCA1 or BRCA2." (PMID 31182966, 2019). "HRDetect identified 44 cancers that carried a germline or a somatic BRCA1/2 variant in a cohort of 560 breast cancer patients and, interestingly, in 47 cancers demonstrating BRCAness in which no pathogenic variant in BRCA1/2 was detected." (PMID 31092228, 2019). "In 1994 and 1995, the first genes associated with susceptibility to breast cancer, BRCA1 (OMIM # 113705) and BRCA2 (OMIM # 600185), were identified." (PMID 31341521, 2019). "In breast cancer, roughly 5–10% of cases are attributed to inherited mutations found in the tumor suppressor BRCA1, and inactivation of the wild type allele promotes tumor initiation." (PMID 31771139, 2019). "We investigated the effect of additional DNA-repair truncating variants on the risk of developing breast cancer among BRCA1 mutation carriers, adjusted for age at menarche, oral contraceptive use, parity and family history." (PMID 31395037, 2019). "In our study, survival analysis revealed that high expression of BRCA1 was linked with breast cancer." (PMID 31311202, 2019). "Germline loss-of-function (LOF) variants in the breast cancer susceptibility genes BRCA1 and BRCA2 are known to result in an approximately tenfold increased lifetime risk of developing breast cancer." (PMID 31757951, 2019). "The well-known breast cancer specific germline mutations in BRCA1 (185delAG; Chr17: 43124030–43124031 and 5382insC; Chr17: 43057065) and BRCA2 (6174delT; Chr13: 32340301) were not amongst the variants identified in either the GBM cohort or the TCGA-GBM cohort." (PMID 32082376, 2019). "The BRCA1 mutation can cause a predisposition to early salivary gland dysfunction, both in patients with breast cancer and in healthy individuals, leading to a decrease in salivary proteins." (PMID 31597313, 2019).
breast cancer (continued). "According to Knudson's model, both alleles of a TSG conferring susceptibility to breast cancer (as BRCA1) need to be mutated to initiate carcinogenesis." (PMID 31518337, 2019). "Prevalence rates are also high among certain ethnicities; 10%–12% of breast cancers in the Ashkenazi Jewish population, unselected for family history, are attributable to mutations in BRCA1 or BRCA2." (PMID 30915162, 2019). "In summary, our study showed that BRCA1/2 mutations account for 24.7% of high-risk breast cancer patients in Pakistan." (PMID 31528241, 2019). "Around 5–10% of all breast cancers are attributed to somatic or germline mutations in the genes BRCA1 and BRCA2." (PMID 31092228, 2019). "BARD1 is a breast cancer susceptibility gene encoding a protein that primarily interacts with BRCA1 in DNA repair." (PMID 30925164, 2019). "Approximately 70% of breast cancers arising in BRCA1 mutation carriers and up to 23% of breast cancers in BRCA2 carriers display a triple negative phenotype." (PMID 30975216, 2019). "The present large single‐institution series supports the oncological efficacy of risk‐reducing bilateral NSM for a variety of indications, including BRCA1/2 and other breast cancer‐associated genes that are increasingly being recognized." (PMID 30957063, 2019). "While somatic BRCA1/2 mutations in breast cancer previously were thought of as rare, compared to germline mutations, contemporary evidence indicates that one third of BRCA mutations have a somatic origin." (PMID 31225507, 2019). "Breast cancer risk is slightly higher among women of Ashkenazi Jewish descent than among other women, likely due to the high prevalence of BRCA1 and BRCA2 pathogenic or likely pathogenic variants in this population." (PMID 30759220, 2019). "In a large study of BRCA1/2 mutation carriers in the CIMBA consortium (11,421 cases/ 10,793 controls), haplogroup T1a1 was inversely associated with breast cancer risk (Hazard Ratio = 0.62; P = 0.03) among BRCA1 carriers of European ancestry." (PMID 31577800, 2019). "It is worth mentioning that not all heritable breast cancers harbor germline variants solely in BRCA1/2, indicating that predisposing variants in other genes likely exist and contribute to hereditary breast cancer via altered mutation accumulation." (PMID 31092228, 2019). "The PI3K pathway has been shown to be activated in a mouse model of BRCA1-mutated breast cancer and the combination of olaparib and BKM120 was synergistic and as such, related to improved efficacy, as compared to either agent alone." (PMID 31374917, 2019). "It is exciting to note that a breast cancer prevention trial is currently underway to treat BRCA1 mutation carriers with denosumab (BRCA‐P)." (PMID 31267556, 2019). "In female carriers of a pathogenic BRCA1 mutation, the average cumulative cancer risk by age 70 is 66% for breast cancer (BC) and 41% for ovarian cancer (OC)." (PMID 31683985, 2019). "In conclusion, we presented five cases of primary breast cancer in patients carrying a BRCA1 or BRCA2 mutation, whose tumors were diagnosed during surveillance." (PMID 30980249, 2019). "In the BRCAsearch study, unselected breast cancer patients were prospectively offered germline BRCA1/2 mutation testing through a simplified testing procedure." (PMID 30311024, 2019). "A large sample screening of high-risk breast cancer patients from Hong Kong showed that LGRs accounted for 6.67% (8/120) of all BRCA1/2 pathogenic variants, involving 8.77% (5/57) of BRCA1 and 4.76% (3/63) of BRCA2, respectively." (PMID 31174498, 2019). "Breast cancer susceptibility gene 1 (BRCA1) is a major breast cancer suppressor gene, which is most frequently mutated in hereditary breast cancer and is often downregulated in sporadic breast cancer." (PMID 30714292, 2019). "A total of 17 BRCA1/2 mutations were detected in 18 of 216 (8.3%) index patients with high‐risk breast cancer." (PMID 30968603, 2019).
breast cancer (continued). "Since the specific sensitivity of tumors with BRCA1/2 mutations to platinum therapy was described in breast cancer and ovarian cancer, we expected the effects to be identical in ESCC." (PMID 30975989, 2019). "We prospectively evaluated the relationship between plasma RANKL and breast cancer risk among women with a BRCA1 or BRCA2 mutation." (PMID 31069010, 2019). "High penetrance breast cancer susceptibility genes — BRCA1 and BRCA2 are responsible only for 5–10% of familial breast cancers." (PMID 31312277, 2019). "The BRCA1 L63X mutation, which was reported only in Asians in the Breast Cancer Information Core database, was identified as a Japanese founder mutation of ovarian cancer in haplotype analysis." (PMID 31143373, 2019). "As with breast cancer mortality and prevalence of the basal-like subtype, the frequency of BRCA1 mutations is higher in AA women." (PMID 33860286, 2019). "Genetic testing can identify mutations associated with cancer risk (e.g., BRCA1/2 for breast cancer), yet only a small fraction of malignancies (about 5% for breast cancer) have a known genetic origin." (PMID 31998733, 2019). "Lifetime risk to develop breast cancer and ovarian cancer is enhanced up to 85% and up to 54% respectively in the carriers of BRCA1 and BRCA2 mutations." (PMID 31608277, 2019). "The connection between BRCA1 mutations and obesity has been investigated, showing that overweight and weight gain increased postmenopausal breast cancer risk in BRCA1/2 mutation carriers." (PMID 31443386, 2019). "To determine the mutational landscape of human BRCA1-mutated breast cancer, we performed a meta-analysis by combining datasets from four large-scale breast cancer sequencing studies and extracting the mutational data of all BRCA1-mutated tumors." (PMID 30674894, 2019). "The polymorphic site, ATF1 rs11169571, was analyzed in a group of ovarian/breast cancer patients with BRCA1 or BRCA2 mutation." (PMID 30905073, 2019). "Maintaining redox balance and committing resources to biosynthesis should be essential for the proliferation of BRCA1‐deficient breast cancer cells." (PMID 30714292, 2019). "We have recently reported the results of the prospective BRCAsearch study, where unselected breast cancer patients were offered germline BRCA1 and BRCA2 mutation testing." (PMID 30311024, 2019). "Subsequently, BRCA1 is proved to be major breast cancer susceptibility genes, whose pathogenic variants are significantly associated with an increased risk of breast and ovarian cancers." (PMID 31065692, 2019). "We, therefore, need to look for BRCA1 germline mutations in patients at risk for hereditary breast cancer." (PMID 31413819, 2019). "In breast cancer specifically, signatures 1B, 2, 3, 8, and 13 were prevalent and strongly associated with BRCA1/2 mutations." (PMID 30934991, 2019). "Women who carry BRCA1/2 mutations have a significantly increased risk of developing breast cancer before the age of 50 years (Couch, Nathanson, & Offit, 2014)." (PMID 31131559, 2019). "This last modifiable risk factor has been described to be significant in decreasing the risk for breast cancer, with a relative risk of 0.63 (95% CI, 0.46–0.86) in mutated BRCA1 populations." (PMID 31331294, 2019). "In a BRCA1-deficient mammary tumor model, the combination of metformin with spautin-1 sensitizes BRCA1-deficient breast tumors to mitochondrial disruptors." (PMID 31013961, 2019).